JDP2 (Jun dimerization protein 2)
Description:
Component of the AP-1 transcription factor that represses transactivation mediated by the Jun family of proteins. Involved in a variety of transcriptional responses associated with AP-1 such as UV-induced apoptosis, cell differentiation, tumorigenesis and antitumogeneris. Can also function as a repressor by recruiting histone deacetylase 3/HDAC3 to the promoter region of JUN. May control transcription via direct regulation of the modification of histones and the assembly of chromatin.
Synonyms: JUNDM2
Tractability: PROTAC: UniProt records ubiquitination sites on it.
Gene: Protein-coding gene on chromosome 14 (75,427,716 to 75,474,111, forward strand). Ensembl gene ENSG00000140044.
Subcellular location: Nucleus
Subcellular location (Human Protein Atlas): Nuclear speckles; Nucleoplasm
Gene Ontology:
Molecular function: DNA-binding transcription repressor activity, RNA polymerase II-specific; protein binding; sequence-specific double-stranded DNA binding; DNA-binding transcription factor activity, RNA polymerase II-specific; RNA polymerase II cis-regulatory region sequence-specific DNA binding; cAMP response element binding; chromatin binding; DNA binding; DNA-binding transcription factor activity; histone chaperone activity; histone deacetylase binding; leucine zipper domain binding; protein heterodimerization activity; protein homodimerization activity
Biological process: negative regulation of transcription by RNA polymerase II; regulation of transcription by RNA polymerase II; regulation of DNA-templated transcription
Cellular component: nucleus; RNA polymerase II transcription regulator complex; chromatin
Genetic constraint (gnomAD): Loss-of-function variants: 9 observed, 16.97 expected, observed/expected ratio (o/e) 0.53, 90% interval 0.32 to 0.93. The upper end of that interval is the gene's LOEUF score, 0.93, which puts it in group 3 of 6, group 1 being the genes least tolerant of losing a copy. Missense variants: 179 observed, 220.49 expected, observed/expected ratio (o/e) 0.81, 90% interval 0.72 to 0.92. Synonymous variants: 107 observed, 97.04 expected, observed/expected ratio (o/e) 1.1, 90% interval 0.94 to 1.29.
Homologues: Orthologues: chimpanzee JDP2 (99% identical), macaque JDP2 (99% identical), guinea pig JDP2 (98% identical), pig JDP2 (98% identical), dog JDP2 (98% identical), mouse Jdp2 (96% identical), rabbit JDP2 (96% identical), rat Jdp2 (96% identical), zebrafish jdp2a (78% identical), zebrafish jdp2b (64% identical), Drosophila melanogaster Atf3 (29% identical). Paralogues in human: ATF3 (48% identical), FOS (37% identical), FOSB (35% identical), FOSL2 (35% identical), FOSL1 (34% identical), BATF3 (24% identical), BATF (21% identical), BATF2 (19% identical).
Diseases named in the same sentence as JDP2 in open-access papers:
JDP2 is named in the same sentence as 61 diseases in open-access papers, as found by Europe PMC text mining. Sharing a sentence is not in itself a finding about the gene and the disease. The quoted sentences say what the papers report.
heart failure (8 papers, 2015 to 2025). Inability of the heart to pump blood at an adequate rate to meet tissue metabolic requirements. "Previous studies showed RNASE4 to be associated with high-altitude adaptation, metabolic syndrome and neuron degeneration, while JDP2 was associated with heart failure." (PMID 28423658, 2017). "Interestingly, in humans, increased JDP2 levels are associated with progression to heart failure after myocardial infarction." (PMID 40710332, 2025). "All together, these analyses demonstrate development of heart failure under prolonged JDP2 overexpression." (PMID 29769710, 2018). "In conclusion, the main finding of this study is that JDP2 overexpression in mice results in premature heart failure development." (PMID 29769710, 2018). "The transcriptional regulator JDP2 (Jun dimerization protein 2) has been identified as a prognostic marker for patients to develop heart failure after myocardial infarction." (PMID 29769710, 2018). "This indicates that under this situation, the unfavorable function of JDP2 prevails and contributes to heart failure progression." (PMID 29769710, 2018). "We now performed in vivo studies on JDP2-overexpressing mice, to clarify the impact of JDP2 on heart failure progression." (PMID 29769710, 2018). "Interestingly, JDP2 is increased in patients after myocardial infarction and was identified as a prognostic marker for heart failure development after myocardial infarction in humans." (PMID 40710332, 2025). "More recently, JDP2 has played roles in atrial fibrillation, cardiac remodeling, and heart failure." (PMID 38473360, 2024). "Another transcriptional regulator, JDP2, could activate the expression of inflammatory genes and promote fibrosis, which has been shown as a prognostic marker for MI patients to develop heart failure." (PMID 34262953, 2021). "However, the observed development of impaired ventricular function within 5 weeks of JDP2 overexpression indicate that those mice probably died of sudden cardiac death or heart failure due to disease progression within 10 weeks." (PMID 33265909, 2020). "However, as heart failure predominantly occurs in the elderly patient, we now determined the role of enhanced JDP2 expression in adult mice hearts." (PMID 29769710, 2018). "Thus, induction of JDP2 is a maladaptive response contributing to heart failure development." (PMID 29769710, 2018).
hepatocellular carcinoma (6 papers, 2010 to 2023). A malignant tumor that arises from hepatocytes. "Previous studies documented that JDP2 acts as a tumor suppressor in hepatocellular carcinoma and pancreatic cancer." (PMID 37179125, 2023). "For example, Yu discovered that miR-501 promoted cell invasion and EMT in hepatocellular carcinoma cells through targeting JDP2." (PMID 37179125, 2023). "To establish the role of JDP2 over-expression in hepatocellular carcinoma, we have generated a tetracycline regulated JDP2 responder transgenic mouse line." (PMID 20214788, 2010). "In hepatocellular carcinoma, miR-501 can regulate JDP2 to promote tumor cell development." (PMID 34869576, 2021). "Similarly, JDP2 prevents AP-1 transcription interfering with the oncogenic properties of c-Jun, but in JDP2 transgenic mice, JDP2 expression in the liver promotes hepatocellular carcinoma." (PMID 30670778, 2019).
liver cancer (6 papers, 2010 to 2025). An epithelial or non-epithelial malignant neoplasm that arises from the liver. "Jdp2 is associated with both liver cancer and bone homeostasis, and is involved in cell differentiation and chromatin remodeling." (PMID 41282178, 2025). "JDP2 is a component of the AP-1 transcription factor that has been shown to be involved in the development of liver cancer in mice." (PMID 34857913, 2022). "For instance, JDP2 has been shown to strengthen the proliferative response and inflammation of the liver cancer model." (PMID 35584452, 2022). "Jdp2 was reported to promote liver transformation as JDP transgenic mice displayed potentiation of liver cancer, higher mortality and increased number and size of tumors." (PMID 27690235, 2016). "The expression of JDP2 at the promotion stage was found to be the most critical for enhancing liver cancer severity." (PMID 20214788, 2010). "We studied three groups of mice in which JDP2 expression was shut-off during different stages of liver cancer development: initiation (group B), initiation + promotion (group C) and progression (group D)." (PMID 20214788, 2010). "In contrast, mice in which JDP2 expression was suppressed during the initiation and promotion stages showed similar liver cancer levels as compared with wild type mice." (PMID 20214788, 2010). "To reveal the role of JDP2 expression in hepatocytes in a liver cancer model, we used a well established chemical carcinogen induced liver cancer protocol." (PMID 20214788, 2010). "We found that JDP2 increases liver cancer severity and that JDP2 expression at the promotion stage is most important for this activity." (PMID 20214788, 2010). "Collectively, JDP2 expression during the promotion stage is found to be important for potentiation of liver cancer by acting as a tumor promoter in the DEN model." (PMID 20214788, 2010). "To assess the role of JDP2 in a different DEN induced liver cancer protocol, we used a second well established protocol in which a single injection of DEN (25 mg/Kg) at 14 days postnatal." (PMID 20214788, 2010). "JDP2-transgenic mice displayed potentiation of liver cancer, higher mortality and increased number and size of tumors." (PMID 20214788, 2010). "Consistently, JDP2-transgenic mice in which transgene expression was suppressed during the first three weeks of life displayed very similar liver cancer severity as compared with a mice cohort in which JDP2 was expressed at all stages." (PMID 20214788, 2010). "To identify the importance of the time of JDP2 expression at the different stages of the development of liver cancer, we took advantages of the ability to shut-off the transgene expression using doxycycline." (PMID 20214788, 2010). "Collectively, using the four weeks DEN liver cancer model, the JDP2-transgenic mice displayed a significantly lower survival rate and increased severity of liver cancer disease." (PMID 20214788, 2010). "It was reported that JDP2 overexpression enhances diethylnitrosamine‐induced liver cancer in mice." (PMID 33108704, 2020). "The increase of CHOP10 expression may provide a possible explanation for JDP2 potentiation of gene transcription at the promotion phase of liver cancer development." (PMID 20214788, 2010). "Collectively, it seems that JDP2 plays a protective role in a cell autonomous manner in vitro but the same process can have a positive outcome in a non cell autonomous way resulting in potentiation of liver cancer." (PMID 20214788, 2010). "JDP2 over-expression potentiaes DEN induced liver cancer development." (PMID 20214788, 2010). "In view of these results, we expected that JDP2 over-expression in the liver will mimic c-Jun disruption and thus may result in inhibition of liver cancer development in this model." (PMID 20214788, 2010).
liver cancer (continued). "In order to examine whether JDP2 increased expression may be a coincidence or may play a role in liver cancer development, we have generated transgenic mice with liver specific JDP2 expression and examined the consequence in a chemically induced liver cancer model." (PMID 20214788, 2010). "Therefore, ATF3 high expression levels observed in the liver of JDP2-transgenic mice may a play a positive role at the tumor promotion stage of liver cancer." (PMID 20214788, 2010). "This study suggests that JDP2 expression may play a critical role in liver cancer development by potentiating the compensatory proliferative response and increased inflammation in the DEN liver cancer model." (PMID 20214788, 2010).
Lewis lung carcinoma (5 papers, 2015 to 2023). "For example, bone marrow-derived cells (BMDCs) secrete chemokines such as Ccl5 that potentiate metastasis, but Jdp2–/– BMDCs do not induce invasion of Lewis lung carcinoma cells." (PMID 37596694, 2023). "Bone marrow–derived cells (BMDCs) secrete chemokines such as CCL5, which potentiate metastasis; however, Jdp2−/− BMDCs do not induce a capacity for invasion in Lewis lung carcinoma cells." (PMID 33723743, 2022). "Here we show that mice lacking JDP2 (JDP2−/−) display a reduced rate of metastasis in Lewis lung carcinoma (LLC) and polyoma middle T-antigen (PyMT) breast carcinoma mouse models." (PMID 26497998, 2015). "In host cells within the tumor microenvironment, it was recently demonstrated that mice lacking ATF3 (ATF3-KO) or JDP2 (JDP2-KO) display a reduced rate of metastasis in polyoma middle T-antigen (PyMT) breast carcinoma mouse model and/or Lewis Lung Carcinoma (LLC)." (PMID 30670778, 2019). "In an additional model, in which Lewis lung carcinoma (LLC) cells were subcutaneously implanted into the flanks of wild-type and JDP2−/− mice, tumors from wild-type mice were found to be relatively smaller than tumors from JDP2 −/− mice, although these differences were not statistically significant." (PMID 26497998, 2015).
pancreatic cancer (5 papers, 2018 to 2023). "Besides, research also discovered an association of epithelial-mesenchymal transition (EMT) with Jun dimerization protein 2 (JDP2) in pancreatic cancer." (PMID 29713243, 2018). "We observed the presence of the AhR-Nrf2 axis in pancreatic cancer 2545 cells and that Jdp2 plays a crucial role in pancreatic cancer progression." (PMID 37596694, 2023). "The effects of DRE-mediated transactivation of Jdp2 on the AhR promoter were investigated in the pancreatic cancer 2545 cell line." (PMID 37596694, 2023). "Liu and Du discovered that overexpressed JDP2 inhibits the EMT in pancreatic cancer BxPC3 cells." (PMID 37179125, 2023). "However, we cannot deny the presence of a time gap between the TCDD induced Jdp2 activation of cell migration and spreading, and pancreatic cancer malignancy." (PMID 37596694, 2023). "Furthermore, JDP2 is relevant to tumor progression and poor prognosis in patients with pancreatic carcinoma." (PMID 35584452, 2022). "miRNA-143-5p has been implicated in the pathophysiology of cancer (including colon and pancreatic cancers) and schizophrenia-related disorders, and its effects on various target genes, such as EMC2, VWC2L, THY1, SGCZ, HIF1, and JDP2, among others, have been described." (PMID 37179125, 2023).
atrial fibrillation (4 papers, 2020 to 2025). A disorder characterized by an electrocardiographic finding of a supraventricular arrhythmia characterized by the replacement of consistent P waves by rapid oscillations or fibrillatory waves that vary in size, shape and timing and are accompanied by an irregular ventricular response. "We performed in vivo studies on JDP2-overexpressing mice to investigate the impact of JDP2 on the predisposition to spontaneous atrial fibrillation (AF)." (PMID 33265909, 2020). "So, if inflammation is not involved in the maintenance of atrial fibrillation under JDP2 overexpression and the reduction of connexin 40 only partially contributes to the atrial fibrillation phenotype, what could be the main causes of AF in JDP2 mice?" (PMID 40710332, 2025). "Therefore, the increase in JDP2 levels after myocardial infarction may contribute to the deterioration of cardiac function by promoting atrial remodeling and the development of atrial fibrillation." (PMID 40710332, 2025). "Heart-specific overexpression of transcriptional regulator JDP2 (jun dimerization protein 2) for 5 weeks provokes paroxysmal atrial fibrillation (AF) in mice." (PMID 40710332, 2025).
breast carcinoma (4 papers, 2011 to 2019). "Here we show that mice lacking JDP2 display a reduced rate of metastasis in lung and breast cancer models (LLC and PyMT, respectively)." (PMID 26497998, 2015). "In the earlier studies on JDP2 interaction with PR, JDP2 had no influence on PR binding to its response element DNA by gel mobility shift assays in vitro and a progesterone stimulated, PR-dependent recruitment of JDP2 by ChIP assay to the MMTV promoter in breast cancer cells was observed." (PMID 22003412, 2011).
glioma (4 papers, 2017 to 2024). A benign or malignant brain and spinal cord tumor that arises from glial cells (astrocytes, oligodendrocytes, ependymal cells). "JDP2 overexpression is associated with an inhibition of epithelial-to-mesenchymal transition which is associated with tumor cell migration and invasion in carcinomas and may also be relevant to glioma cell migration and invasion." (PMID 28460484, 2017). "In fact, the marker genes of the GABRA receptor families and cystine transporter xCT (SLA7A11 and CD44v), as well as antioxidation-controlled factors, such as JDP2, NRF2, and CDKN1A (p21Cip1), were significantly mutated in brain tumors, e.g., glioblastoma, glioma, and neuroblastoma." (PMID 39695141, 2024). "On the other hand, JDP2 knockdown also increased TRAIL sensitivity of T98G human glioma cells." (PMID 33108704, 2020).
lymphoma (4 papers, 2016 to 2025). A malignant (clonal) proliferation of B- lymphocytes or T- lymphocytes which involves the lymph nodes, bone marrow and/or extranodal sites. "Importantly, Jdp2 was identified in a screen for oncogenes able to collaborate with the loss of p27kip1 cyclin-dependent inhibitor to induce lymphomas." (PMID 27690235, 2016).
medulloblastoma (4 papers, 2013 to 2024). A malignant, invasive embryonal neoplasm arising from the cerebellum. "We generated iPSC-like cells form DAOY medulloblastoma cell by introducing JDP2 and the defining factor OCT4." (PMID 24202329, 2013). "The induced pluripotent stem cells (iPSC)-like cells were generated from DAOY medulloblastoma cell by introduction of JDP2, and the defined factor OCT4." (PMID 24202329, 2013). "We studied the characteristics of the reprogrammed medulloblastoma cells because JDP2 was expressed predominantly in the cerebellar granule cells." (PMID 24202329, 2013). "We reprogrammed medulloblastoma cells to generate iPSC-like cells using the transduction of lentivirus-encoded JDP2 and OCT4 to characterize the reprogrammed medulloblastoma iPSC-like cells." (PMID 24202329, 2013). "We generated iPCSCs from a medulloblastoma cell line (DAOY cells) using OCT4 and JDP2 to induce cell reprogramming." (PMID 38791215, 2024). "This study showed that the antioxidant-induced transcription factor JDP2 modulates ROS activity and that addition of JDP2 and OCT4 led to reprogramming of DAOY medulloblastoma cell to iPSC-like cells." (PMID 24202329, 2013). "We also reprogrammed human medulloblastoma cells, such as DAOY, using JDP2 and OCT4." (PMID 38791215, 2024). "In addition, we produced iPCCs from a DAOY medulloblastoma cell line using OCT4 and Jun dimerization protein 2 (JDP2) transcription factors for reprogramming." (PMID 35629138, 2022).
T-cell lymphoma (4 papers, 2008 to 2025). "Retroviral activation of alternative Jdp2 in T cell lymphomas of mice has been reported, providing the strong evidence for a gain-of-function of Jdp2 in cancer development in the hematopoietic system." (PMID 24202329, 2013). "On the other hand, the JDP2 locus was found at a recurring viral integration site in T-cell lymphoma." (PMID 20214788, 2010). "Retroviral activation of JDP2 in T-cell lymphomas of mice is the only evidence for a gain-of-function potential of JDP2 in cancer development." (PMID 20214788, 2010). "Moreover, JDP2 locus was identified at viral integration sites resulting in T cell lymphoma." (PMID 20214788, 2010).